S100A9 (S100 calcium binding protein A9)
Diseases named in the same sentence as S100A9 in open-access papers (continued):
Sharing a sentence is not in itself a finding about the gene and the disease.
Sepsis (continued). "Western blotting using whole cell extracts showed that treatment with GSK-J4 remarkably increased levels of phospho-S100A9 protein in late sepsis Gr1+CD11b+ cells." (PMID 39665047, 2023). "Our findings that Hotairm1 knockdown in late sepsis MDSCs from mice and humans increased S100A9 phosphorylation and reduced IL-10 production are biologically significant." (PMID 39665047, 2023). "Previous studies, including ours, have reported that targeting S100A9 function attenuated sepsis-induced lung damage by inhibiting the inflammatory response." (PMID 37978525, 2023). "Our previous studies showed that Hotairm1 modifies the S100A9 protein’s function to generate MDSCs during later sepsis." (PMID 35185915, 2022). "Numerous studies have shown that S100A9 is upregulated in various inflammatory and infectious diseases, including sepsis and patients with severe COVID-19 infection." (PMID 35957694, 2022). "We reported that sepsis MDSC development requires long non-coding RNA Hotairm1 interactions with S100A9." (PMID 35185915, 2022). "The convergence on these findings has been hinted in mouse models of late sepsis, where S100A9 stabilizes the Stat3-C/EBPβ protein complex that activates the miR-21 and miR-181b promoters." (PMID 35986237, 2022). "Hotairm1 shuttles S100A9 protein to the nucleus in myeloid precursors to program them into MDSCs during later sepsis." (PMID 35185915, 2022). "The immunosuppressive IL-10 cytokine, whose levels increase significantly during later sepsis, promotes the Hotairm1-mediated shuttling of S100A9 protein to the nucleus in MDSCs." (PMID 35185915, 2022). "Herein, we observed that ABR-238901 antagonized CLP-induced leukocytopenia, indicating that S100A9 also controls systemic inflammation in sepsis." (PMID 34884728, 2021). "Our results suggest that S100A9 promotes neutrophil activation and pulmonary accumulation in sepsis." (PMID 34884728, 2021). "Study have reported that patients with higher serum S100A9 expression tended to suffer from more severe sepsis-related organ dysfunction." (PMID 33863396, 2021). "S100A9 secretion significantly increased following stimulation with LPS, and was increased further slightly in the presence of exosomes from sham or early sepsis Gr1+CD11b+ cells." (PMID 33335790, 2020). "These exosomes inhibited lipopolysaccharide-stimulated secretion of S100A9 from early sepsis Gr1+CD11b+ cells." (PMID 33335790, 2020). "We also found that narciclasine effectively reduced the S100A8 and S100A9 mRNA expression in the livers when compared to the untreated sepsis group." (PMID 32076015, 2020). "Re-localization of S100A9 protein from cytosol to nucleus of Gr1+CD11b+ cells occurs during late sepsis." (PMID 33335790, 2020). "Narciclasine effectively suppressed the S100A8 and S100A9 protein expression in the livers of neonatal septic rats compared to the untreated sepsis group." (PMID 32076015, 2020). "The major finding of this study is that Hotairm1 dependent translocation of S100A9 protein from the cytosol to the nucleus in Gr1+CD11b+ myeloid precursors predominates during the late/chronic stage of sepsis and supports the MDSC repressor function." (PMID 33335790, 2020). "S100A9 expression markedly increases during early/acute sepsis, but significantly decreases in late septic mice concurrently with its translocation to the nucleus in Gr1+CD11b+ MDSCs." (PMID 33335790, 2020). "In support of translating the mechanistic concept to human sepsis, we found that Hotairm1 binds S100A9 protein in CD33+CD11b+HLA-DR− MDSCs during established sepsis." (PMID 33335790, 2020). "This shows the potential influence and effect of the S100A8, S100A9 proteins in conditions like sepsis and shock and the need to neutralize its deleterious effects." (PMID 32076015, 2020).
Sepsis (continued). "Since genetic targeting of S100A9 in mice limits MDSC expansion and sepsis-associated immunosuppression, molecular targeting of Hotairm1 is a plausible drug target for reversing sepsis-induced chronic immunosuppression." (PMID 33335790, 2020). "By contrast, a continuous and gradual increase in the levels of IL-10 was observed in the wild-type mice especially after 6 days of the onset of sepsis, while a slight elevation in IL-10 was observed in S100A9 knock-out mice during the early septic phase only." (PMID 32931721, 2020). "Together, these results indicate that Hotairm1 mediates S100A9 protein localization in the nucleus in Gr1+CD11b+ MDSCs in late sepsis." (PMID 33335790, 2020). "Mechanistically, increased Hotairm1 expression in MDSCs in mice converted S100A9 from a secreted proinflammatory mediator to an immune repressor by binding to and shuttling it from cytosol to nucleus during late sepsis." (PMID 33335790, 2020). "In this study we made the novel observation that exosomes shed from late sepsis Gr1+CD11b+ MDSCs inhibited the LPS-induced secretion of S100A9 from early sepsis Gr1+CD11b+ cells." (PMID 33335790, 2020). "In contrast, and after day 6 in our model, sepsis Gr1+CD11b+ cells become immunosuppressive, with higher levels of S100A9 protein in the nucleus." (PMID 33335790, 2020). "Narciclasine treatment showed significant reduction of S100A8 and S100A9 levels in the lung and liver homogenates compared to the untreated sepsis group." (PMID 32076015, 2020). "S100A9 localizes mainly in cytosol during acute sepsis, but moves to the nucleus as immunosuppressive Gr1+CD11b+ MDSCs emerge." (PMID 33335790, 2020). "Next, we investigated Hotairm1-S100A9 interactions using early sepsis Gr1+CD11b+ cells, where S100A9 protein resides mainly in the cytosol." (PMID 33335790, 2020). "Besides these pro-inflammatory properties of S100A9, there are also anti-microbial effects associated with S100A9 expression, as in pneumonia-induced sepsis, where S100A9 reduces bacterial growth; whether this effect is mediated by EMMPRIN is similarly still unknown." (PMID 29419744, 2018). "S100A9 expression is significantly upregulated in the early stage of Klebsiella pneumoniae infection-induced sepsis." (PMID 29942307, 2018). "In septicemia-induced septic shock, the expression of S100A9 is continuously increased until the patient’s death." (PMID 29942307, 2018). "Several studies have been reported the correlation of S100A9 with inflammatory disease, including rheumatoid arthritis, inflammatory bowel disease and sepsis." (PMID 29615081, 2018). "Most importantly, we found that S100A9 protein was mainly localized in thenuclear compartment in late sepsis Gr1+CD11b+cells (i.e., MDSCs)." (PMID 29204146, 2017). "Tantamount to molecular targeting therapeutics, genetic deletionof S100A9 in mice improves chronic sepsis mortality." (PMID 29204146, 2017). "S100A9 protein was mainly detected in the cytosol inGr1+CD11b+ cells in early sepsis, but wasmainly localized in the nucleus in late sepsis." (PMID 29204146, 2017). "As shown inFigure 3A, TNFα levels increased in bothwild-type and S100A9 knockout mice during early sepsis, but were significantly higherin wild-type mice." (PMID 29204146, 2017). "These resultssupport that improved sepsis survival in the S100A9 knockout mice parallels reducedimmunosuppressive cytokine production and increased local bacterial clearance." (PMID 29204146, 2017). "Numbers of Gr1+CD11b+cells significantly increased in the bone marrow in wild-type and S100A9 knockoutmice in early sepsis, as we reportedpreviously, but were significantlydecreased in the S100A9 knockout mice in late sepsis." (PMID 29204146, 2017). "S100A9 mRNA andintracellular protein levels increase during early sepsis and remain elevated inGr1+CD11b+ MDSCs after pro-inflammatorysepsis transitions to the later chronic anti-inflammatory and immunosuppressivephenotype." (PMID 29204146, 2017).
Sepsis (continued). "Because S100A8 protein is diminished in theS100A9 knockout mice, we examinedwhether reconstitution of the S100A9 knockout mice with S100A8 and/or S100A9 affectslate sepsis responses." (PMID 29204146, 2017). "S100A9-/- mice showed decreased hepatocellular inflammation compared to WT mice in an E. coli induced sepsis model." (PMID 25860480, 2015). "The expression of ApoE, Anxa1, NGAL, S100a8 and S100a9 were all elevated in the progression of sepsis." (PMID 25242054, 2014). "S100a8 and S100a9 as members of the S100 protein family, are released from neutrophils and activate phagocytes during sepsis." (PMID 25242054, 2014). "In conclusion, the present study demonstrated that the expression of five proteins (ApoE, Anxa1, NGAL, protein S100a8 and S100a9) was significantly elevated in the progression of sepsis." (PMID 25242054, 2014). "In the current study, we thus evaluated the regulation of S100A8 and S100A9 mRNA expressions in an ex vivo model of sepsis-induced immune dysfunctions (endotoxin tolerance)." (PMID 24956170, 2014). "The present study indicated that the expression of S100a8 and S100a9 were significantly elevated in the lymph during early stages of sepsis (CLP-6h) but decreased in later stages (CLP-24h)." (PMID 25242054, 2014). "As outlined in a previous study, the S100a8/S100a9 plasma levels were significantly elevated in patients with severe sepsis." (PMID 25242054, 2014). "In abdominal sepsis patients, the S100a8/S100a9 levels in the abdominal fluid were >15-fold that in the plasma, indicating that S100a8/S100a9 expression was induced primarily at the site of infection during sepsis." (PMID 25242054, 2014). "Previously it was shown that S100A9 KO mice were protected against mortality induced by endotoxic shock and E.coli induced sepsis suggesting a detrimental role during systemic inflammation and infection." (PMID 20976233, 2010). "Recently it was shown that S100A9 KO mice were protected against mortality during E. coli-induced sepsis showing its contribution in systemic infection." (PMID 20976233, 2010). "Moreover, in the test datasets, the expression of LILRA5, MGST1, PLBD1, and S100A9 was significantly elevated in the sepsis group." (PMID 40792106, 2025). "S100A9protein assembled at IL-10 and TGF-β promoters in MDSCs during late sepsis inmice and humans, and S100A9 could activate a reporter genecontrolled by IL-10 or TGF-β promoter." (PMID 40458301, 2025). "Predictive value of S100A9 for 28-day mortality in patients with sepsis." (PMID 40478888, 2025). "Similarly, in sepsis-induced acute liver injury, S100A9 exacerbates liver dysfunction and injury by regulation of AKT-AMPK-dependent mitochondrial energy metabolism." (PMID 40630623, 2025). "Notably, invivo depletion of long noncoding Ribonucleic Acid (RNA)Hotairm1, which induces S100A9 proteinaccumulation in MDSCs during late sepsis, reduced IL-10 and TGF-βproduction ex vivo." (PMID 40458301, 2025). "Tasquinimod and Paquinimod are currently commonly used pharmacological inhibitors of S100A9, and it has been found that inhibiting S100A9 with Paquinimod can reduce sepsis induced mitochondrial dysfunction, oxidative stress, and immunosuppression through multiple pathways." (PMID 40108736, 2025). "Also, the authors highlighted the beneficial effects of S100A9 inhibition on systolic function and mortality in their model of sepsis-induced cardiomyopathy." (PMID 40948795, 2025). "The median concentrations of S100A9 on admission were 364.43 pg/ml (203.40, 561.56) in patients with sepsis, 747.82 pg/ml (430.63, 1501.63) in patients with septic shock, 280.99 pg/ml (184.11, 457.12) in non-septic ICU patients, and 268.20 pg/ml (134.97, 358.10) in healthy controls." (PMID 40478888, 2025). "Difference of S100A9 concentrations between sepsis groups according to the APACHE II score." (PMID 40478888, 2025).
Sepsis (continued). "Accumulation of S100A9 protein in thenucleus supports the immunosuppressive function of MDSCs, suggesting that nuclearS100A9 may act as an immune repressor during late sepsis." (PMID 40458301, 2025). "Furthermore, survival curve analysis highlighted that sepsis patients with high serum S100A9 levels at admission had a lower survival rate." (PMID 40478888, 2025). "Notably, molecular docking and long-term molecular dynamics (MD) simulations demonstrated that Maralixibat binds stably to the S100A9 protein, a critical DAMP driving sepsis-associated immune suppression." (PMID 41303672, 2025). "We therefore hypothesize that S100A9 may be elevated in the early stage of sepsis, and may serve as a potential biomarker for early diagnosis of septic shock." (PMID 40478888, 2025). "Characteristics of serum S100A9 level fluctuations in sepsis patients." (PMID 40478888, 2025). "First, S100A9 is aligned with the progression and prognosis of sepsis." (PMID 40478888, 2025). "Weidentified nuclear S100A9 as an immune repressor switch in MDSCsbecause S100a9-deficient mice do not generate immunosuppressiveMDSCs and survive sepsis." (PMID 40458301, 2025). "We screened a signature featuring three programmed cell death related genes (NLRC4, TXN and S100A9) and found that it could predict the occurrence of sepsis." (PMID 40028203, 2025). "The discovery of these pro-inflammatory mechanisms may be able to reasonably explain the increased serum S100A9 concentrations among sepsis patients." (PMID 40478888, 2025). "In our study, we combined S100A9 with other multimarkers to predict 28-day mortality in sepsis." (PMID 40478888, 2025). "In numerous studies related to sepsis, S100A9 plays an active pro-inflammatory role." (PMID 40478888, 2025). "Since IL-10 and TGF-β enhance sepsisimmunosuppression and are associated with worse outcomes, our findings suggestthat targeting S100A9 may mitigate the immunosuppressiveeffects of MDSCs in late sepsis." (PMID 40458301, 2025). "The inhibition of S100A9 with drugs and inhibitors markedly attenuates brain injury after subarachnoid hemorrhage, reduces mortality rates in murine models of sepsis and traumatic brain injury, and improves the viability and survival rate of neurons after spinal cord injury." (PMID 39125762, 2024). "Finally, we selected six DEPs that were closely associated with sepsis: cathepsin B (CatB), vascular endothelial cell adhesion molecule (VCAM-1), neutrophil gelatinase-associated lipoprotein (NGAL), protein S100-A9, prosaposin, and thrombospondin-1 (TSP-1)." (PMID 39049003, 2024). "Notably, Hotairm1 transcripts were detected in the S100A9 protein complex at a significantly higher level in late sepsis Gr1+CD11b+ cells." (PMID 39665047, 2023). "We have previously shown that IL-10 production is associated with MDSC accumulation in mice during late sepsis and that mice lacking the S100a9 gene do not generate immunosuppressive MDSCs and have significantly less IL-10." (PMID 39665047, 2023). "This study reveals a previously unknown role of S100A9 in accelerating sepsis-induced hepatic dysfunction and injury." (PMID 36768433, 2023). "Because siRNA-mediated knockdown of Hotairm1 in late sepsis Gr1+CD11b+ cells increased S100A9 phosphorylation by p38 MAPK, we investigated whether inhibition of KDM6A demethylase activity can affect S100A9 protein phosphorylation." (PMID 39665047, 2023). "Furthermore, we demonstrated that administration of the S100A9 inhibitor Paq to mice also prevented sepsis-induced liver dysfunction upon CLP operation." (PMID 36768433, 2023). "In addition, our findings demonstrated a significant decrease in sepsis-induced pulmonary vascular leakage in S100A9 KO mice, as evidenced by the reduced EB extravasation in the lung (n = 6)." (PMID 37978525, 2023). "Importantly, we found that the S100A9 protein translocates to and accumulates in the nucleus in MDSCs in mice and humans during protracted sepsis." (PMID 39665047, 2023).
Sepsis (continued). "We determined whether the increase in S100A9 phosphorylation following Hotairm1 knockdown decreased IL-10 levels in late sepsis Gr1+CD11b+ cells." (PMID 39665047, 2023). "Notably, phosphorylation of the S100A9 protein is diminished in Gr1+CD11b+ cells during the late sepsis phase." (PMID 39665047, 2023). "Therefore, this study shows that S100A9 is a critical contributor to septic liver dysfunction and highlights S100A9 as a potential therapeutic target for treating sepsis and liver dysfunction." (PMID 36768433, 2023). "Therefore, this study demonstrates that S100A9 has an impact on sepsis-induced AKI, and emphasizes targeting S100A9 as a potential therapeutic option for this disease." (PMID 37547329, 2023). "A study found that targeting S100A9 could reduce neutrophil recruitment and lung accumulation in sepsis, thereby improving sepsis-related lung injury." (PMID 37671148, 2023). "Next, we investigated whether S100A9 KO affects CLP-induced hepatic inflammation and ROS production, both of these effects being associated with sepsis-induced ALI." (PMID 36768433, 2023). "Furthermore, the current study primarily focused on evaluating the effect of S100A9 KO on sepsis-induced pulmonary vascular leakage and found that S100A9 KO resulted in decreased pulmonary vascular extravasation of EB." (PMID 37978525, 2023). "Notably, increasing S100A9 protein phosphorylation in late sepsis MDSCs via Hotairm1 knockdown decreases the production of the immunosuppressive cytokine IL-10." (PMID 39665047, 2023). "During late sepsis, S100A9 protein moves from the cytosol to the nucleus in Gr1+CD11b+ MDSCs, concurrent with increases in Hotairm1 transcripts, and knockdown of Hotairm1 results in the shuttling of S100A9 protein back to the cytosol." (PMID 39665047, 2023). "Our results suggest that Hotairm1 dysregulates S100A9 protein function and activity by phosphorylation, which could inform sepsis therapeutic targeting." (PMID 39665047, 2023). "Furthermore, our findings revealed that S100A9 remained elevated in the circulation of individuals, revealing a strong connection with sepsis diagnosis." (PMID 37978525, 2023). "In summary, Hotairm1 prevents the phosphorylation of S100A9 protein in MDSCs during late sepsis." (PMID 39665047, 2023). "Furthermore, a receiver operating characteristic curve was constructed to evaluate the sensitivity of S100A9 plasma levels for diagnosing sepsis." (PMID 37978525, 2023). "We reported that calcium-binding protein S100A9 promotes MDSC development during murine sepsis." (PMID 39665047, 2023). "The expression of S100A9 was significantly elevated in the in vitro model of endotoxin tolerance, suggesting that S100A9 may be a novel biomarker of endotoxin tolerance and providing valuable information for immunotherapy in patients with sepsis shock." (PMID 36439140, 2022). "They performed eloquent experiments reconstituting S100A9 protein to Gr1+CD11b+ cells from S100A9 knockout mice with late sepsis and found that it restored the Stat3-C/EBPβ protein complex and miR-21 and miR-181b expression, and resulted in the immunosuppressive, MDSC phenotype." (PMID 35986237, 2022). "By targeting KDM6A demethylase activity, S100A9 nuclear accumulation decreased in MDSCs, supporting the report that mice deficient in S100A9 do not generate MDSCs during sepsis." (PMID 35185915, 2022). "In this study, we used GSK-J4 treatment to relocate S100A9 to the cytosol in later sepsis MDSCs." (PMID 35185915, 2022). "Based on the considerations above, we hypothesized that targeting S100A9 might reduce secretion of pro-inflammatory mediators, accumulation of neutrophils and tissue damage in sepsis-induced lung damage." (PMID 34884728, 2021). "Increased formation of S100A9 is observed in patients with sepsis and severe COVID-19 infection." (PMID 34884728, 2021).